INS (insulin)
Diseases named in the same sentence as INS in open-access papers (continued):
Sharing a sentence is not in itself a finding about the gene and the disease.
diabetes (continued). "Effective management of type 1 diabetes mellitus focuses on maintaining optimal glycemic control, primarily through exogenous insulin therapy." (PMID 40806227, 2025). "Animal studies have demonstrated that increased vegetable intake reduces body weight, plasma glucose, and insulin resistance, thereby contributing to improved glucose and insulin homeostasis and potentially preventing diabetes." (PMID 41227672, 2025). "This condition typically resembles type 1 diabetes mellitus, characterised by its abrupt onset and an immediate requirement for insulin therapy." (PMID 41018379, 2025). "Fouad found that patients with diabetes had greater levels of periradicular disease and periodontal disease symptoms after having endodontic therapy, and that patients on insulin had a propensity to have more flare-ups." (PMID 40308406, 2025). "Of the 19 metabolic studies, 13 were further classified as diabetic, since they modeled insulin and glucose metabolism in the context of patients with diabetes." (PMID 41028914, 2025). "Obesity, especially abdominal obesity, contributes through inflammation and insulin resistance, while long-standing diabetes promotes tumor growth through hyperglycemia and elevated insulin levels." (PMID 40591568, 2025). "Diabetes mellitus, a metabolic disorder characterized by hyperglycemia due to inadequate insulin secretion and utilization, involves non‐Hippo pathway‐dependent YAP activation, which drives the progression of diabetes‐related atherosclerosis." (PMID 40066231, 2025). "Our STZ-treated mouse model induces diabetes by ablating insulin-producing pancreatic β cells of mice." (PMID 39937900, 2025). "Type 1 diabetes mellitus (T1DM) is characterized by high blood sugar levels secondary to low blood insulin levels due to the autoimmune destruction of pancreatic beta islet cells." (PMID 40270966, 2025). "NAMs provide critical insights into how chemicals impair insulin production and disrupt glucose metabolism, contributing to conditions like diabetes and metabolic disorders." (PMID 39857315, 2025). "Prandial insulin analogs compensate for the spike in blood glucose where high insulin demand is needed after meals with progressive diabetes." (PMID 40156735, 2025). "It is standard practice for CDCES to teach youth with diabetes and their family/caregivers to safely manage and adjust their own insulin doses." (PMID 41283065, 2025). "Tannin extracts from grape residues have shown promising effects in the prevention and complementary treatment of obesity and diabetes by modulating adipogenesis, improving insulin sensitivity, and reducing oxidative stress." (PMID 40649244, 2025). "It is well established real-time, point-of-care capabilities for insulin sensing would provide valuable insight to enhance diabetes management and care in the human body." (PMID 40200746, 2025). "This approach offers a more flexible diet for people with diabetes by tailoring the insulin dosage to the amount of carbohydrates consumed." (PMID 41477679, 2025). "Disruptions in amino acid transport can lead to significant metabolic abnormalities in diabetes, characterized by impaired insulin signaling and altered glucose metabolism." (PMID 40469683, 2025). "Insulin has a crucial role in diabetes treatment, but irregular injection behaviors are prevalent among elderly diabetic patients." (PMID 41180388, 2025). "The higher prescription of insulin analogs in T1DM aligns with Brazilian Diabetes Society guidelines, recommending long-acting and short-acting analogs for better glycemic control and reduced hypoglycemia events." (PMID 39901274, 2025). "Diabetes mellitus (DM) is a long-term metabolic disease characterized by constantly elevated blood glucose levels, either due to insufficient insulin production or the body’s inability to effectively use the insulin it produces." (PMID 40597598, 2025).
diabetes (continued). "Initially, in pre-DSEP training, most of the diabetes knowledge was poor to fair, with the lowest in areas of insulin therapy, glucose monitoring, and diabetic foot exams." (PMID 40126315, 2025). "With the progression of the disease, patients exhibited increased fasting glucose and insulin levels, suggesting the development of Type 2 diabetes mellitus (T2DM) and insulin resistance." (PMID 40283113, 2025). "Genetic variation in the glucokinase gene (GCK) can change the threshold for GSIS, resulting in either elevated fasting glucose levels and/or diabetes or inappropriate secretion of insulin at low blood glucose levels." (PMID 41516031, 2025). "Antioxidant supplementation has also been shown to improve endothelial function, insulin sensitivity, and glucose metabolism, contributing to better glycemic control and overall management of diabetes." (PMID 41488875, 2025). "Diabetes mellitus (DM) is characterized by persistent hyperglycemia due to impaired insulin secretion, resistance to insulin’s peripheral actions, or both." (PMID 40809178, 2025). "This chronic inflammation will interfere with insulin signaling, reduce the effect of insulin, and further aggravate the condition of diabetes." (PMID 40860483, 2025). "This proliferation defect ultimately reduces normal INS+ β-cell populations, contributing to neonatal diabetes development." (PMID 40943666, 2025). "Diabetes is a chronic metabolic disorder that occurs when the glucose level of the blood increases and the body cannot produce or use insulin effectively." (PMID 41153292, 2025). "Diabetes management is a dynamic and evolving field, particularly as the need for insulin therapy arises in both type 1 (T1D) and type 2 diabetes (T2D)." (PMID 40509887, 2025). "Compromise of the pancreas can result in pancreatogenic diabetes mellitus, which arises due to destruction of insulin-producing islet cells." (PMID 40443601, 2025). "This is noteworthy, as interleukins are central markers of inflammation, also present in diabetes, and represent key targets of pharmacological and insulin-based therapies." (PMID 40943671, 2025). "Compared to T1DM patients, WS patients show lower daily insulin requirements, lower average HbA1c levels, lower incidence of diabetic ketoacidosis and microvascular complications, and higher incidence of severe hypoglycemia." (PMID 40641032, 2025). "• Higher incidence of new-onset diabetes and hyperglycemia in COVID patients.• Increased risk of new-onset diabetes by about 40% following SARS-CoV-2 infection.• Pancreatic islet cell stress, reduced insulin expression, and β-cell apoptosis, has been observed." (PMID 41488148, 2025). "The effect of aerobic exercise on blood glucose concentration in dogs with experimentally induced insulin-treated diabetes has also been studied." (PMID 40612145, 2025). "Some evidence suggests that reduced NO bioavailability in obesity and diabetes negatively affects insulin secretion, whereas other studies indicate that NO can inhibit glucose-stimulated insulin secretion." (PMID 40564010, 2025). "Our findings regarding diabetes treatment modalities revealed that subjects treated with tablets and tablets plus insulin presented significantly lower odds of adhering to PA recommendations than did those managed with diet alone." (PMID 40287659, 2025). "This study aims to evaluate the impact of a digital application on self-management (ESYSTA, Germany), expressed in a change in HbA1c levels, in people with diabetes treated with insulin." (PMID 40661654, 2025). "In summary, “Meein” fruit extract showed significant benefits in a T2D mouse model by reducing insulin levels, lowering fasting blood glucose, and limiting diabetes-related weight gain, indicating improved insulin sensitivity and glycemic control." (PMID 40895680, 2025).
diabetes (continued). "Our findings align with previous observational studies suggesting a potential protective role of DPP-4 inhibitors in patients with type 2 diabetes mellitus and COVID-19, particularly among those receiving insulin therapy." (PMID 40869643, 2025). "Subjects identified the need for accurate recording of insulin self‐administration on hospital records to support measurement of the function “Arrange self‐management of diabetes while in hospital” (foreground function)." (PMID 40696540, 2025). "Insulin is a key therapy for the treatment of diabetes and is used in patients suffering from severe COVID-19 accompanied by hyperglycemia." (PMID 40469441, 2025). "In today's society, diabetes mellitus, a chronic metabolic condition of glucose-insulin homeostasis, is on the rise." (PMID 40734861, 2025). "For example, in the WoS dataset, TWOR matches a topic centered on Diabetes (e.g., “insulin,” “glucose,” “obesity”), while KL divergence instead retrieves bioelectromagnetic topics, likely due to similar growth patterns rather than shared semantics." (PMID 40567690, 2025). "On the contrary, patients on insulin therapy for diabetes had a higher prevalence of NAFLD (40% in the NAFLD group vs. 25% in the non-NAFLD group) (p ≤ 0.001)." (PMID 40630376, 2025). "Diabetes mellitus (DM) is a worldwide chronic metabolic disorder characterized by high blood sugar and glucose in the urine due to inadequate insulin production or reduced insulin sensitivity in target cells." (PMID 41198625, 2025). "This review synthesizes current knowledge on the secretion mechanisms of insulin, glucagon, somatostatin, ghrelin, and pancreatic polypeptides, emphasizing their functional crosstalk in diabetes." (PMID 40919135, 2025). "SHAP showed that the most important predictors of DR were TyG, insulin therapy, diabetes course, HbA1c, and HDL." (PMID 41293734, 2025). "Patients with diabetes need to inject insulin lifelong or take other glucose-lowering drugs, contributing to substantial economic costs." (PMID 40988682, 2025). "Diabetes is a chronic metabolic disease characterized by hyperglycemia, resulting from defects in insulin secretion, insulin action or both." (PMID 40901823, 2025). "Diabetes mellitus is a chronic metabolic disorder characterized by hyperglycemia resulting from defects in insulin secretion, insulin action, or both." (PMID 40895989, 2025). "The presence of diabetes during gestation is characterized by the disordered secretion and metabolism of insulin, leading to hyperglycemia." (PMID 41007128, 2025). "This is consistent with previous studies that demonstrate high sucrose diets induce diabetes-like phenotypes as a result of impaired insulin signalling." (PMID 40845064, 2025). "The absence of insulin hepatic cells contributes to hyperglycaemia in patients with diabetes despite subcutaneous administration of insulin due to its poor circulation to the liver." (PMID 41155876, 2025). "Diabetes mellitus is identified as a metabolic disorder with either an absolute or relative shortage of insulin and/or resistance to insulin in the organs it affects." (PMID 41140404, 2025). "She developed diabetes mellitus at the age of 10 years and was treated with insulin, given as multiple daily injections totaling 0.9 units per kg per day." (PMID 40842493, 2025). "Currently, oral hypoglycemic medicines and injections of exogenous insulin are generally used for diabetes mellitus treatment." (PMID 40278571, 2025). "Local complications of insulin therapy are common in patients with diabetes, such as infections and lipodystrophy, the latter having the greatest impact on metabolic control." (PMID 40072991, 2025). "In diabetes, sirtuins have a protective function by improving insulin sensitivity, reducing inflammation, and regulating glucose metabolism." (PMID 41304967, 2025).
diabetes (continued). "Their study showed that functionalities for a calculation device for insulin doses, diary for meals and carbohydrate intake, reminders to check blood glucose, and contact details for their diabetes team were wanted features in future diabetes apps." (PMID 40029895, 2025). "People with diabetes use insulin and synthetic anti-diabetic medications to regulate their glucose levels." (PMID 40563879, 2025). "Diabetes: For pretransplant diabetes, insulin therapy is often necessary, particularly in the perioperative period." (PMID 40218153, 2025). "As a result, insulin delivery systems based on natural polymers can significantly enhance the management of diabetes." (PMID 40352348, 2025). "The β-cell dedifferentiation and impaired glucose-stimulated insulin secretion (GSIS) contribute to the pathogenesis of diabetes." (PMID 41473243, 2025). "Nine chapters have been provided including minimum standards of diabetes care, insulin regimens, avoiding hospitalisation and discharge planning." (PMID 39500566, 2025). "Diabetes mellitus is a long-term metabolic condition characterized by persistent hyperglycemia due to reduced insulin production, insulin resistance, or both." (PMID 40565947, 2025). "Advanced hybrid closed-loop (aHCL) systems have revolutionized diabetes management by automating insulin adjustments based on real-time glucose levels." (PMID 41464725, 2025). "ChatGPT's responses to questions about insulin and oral diabetes medication prior to colonoscopy were consistent with guidelines from the ADS." (PMID 40698206, 2025). "Among 750 consecutive screened subjects with type 2 diabetes, 98 (13%) had diabetic neuropathy (mean age 66.7 ± 7.6 years, diabetes duration 11.3 ± 6.7 years, HbA1c 8.1 ± 1.5%, 43.8% insulin-treated)." (PMID 40564126, 2025). "Type 2 diabetes mellitus (T2DM), which accounts for approximately 90–95% of all diabetes cases, is primarily caused by insulin resistance and inadequate insulin secretion." (PMID 40872202, 2025). "Several randomized controlled trials (RCTs) and case reports involving individuals with metabolic syndrome or diabetes have demonstrated potential benefits of TRE, including reductions in fasting glucose, improvements in insulin sensitivity, and weight loss." (PMID 40806442, 2025). "In the context of diabetes, reduced insulin sensitivity and chronic hyperglycaemia downregulate PGC-1α expression, leading to impaired mitochondrial biogenesis." (PMID 40243689, 2025). "For instance, bitter melon extracts have been shown to lower blood glucose levels and improve insulin sensitivity in animal models of diabetes." (PMID 40686811, 2025). "Many people with diabetes use insulin therapy, a subcutaneous injectable treatment that regulates blood glucose levels." (PMID 41358572, 2025). "Pancreatic dysfunction, particularly the impairment of β-cells responsible for insulin secretion, is a pivotal factor in the development of diabetes." (PMID 40260393, 2025). "Within the diabetes subgroup, patients were receiving various antidiabetic treatments: metformin (n = 21), insulin (n = 9), SFN (n = 19), TZD (n = 4), DPP-4i (n = 11), GLN (n = 4), and AGi (n = 13)." (PMID 40299501, 2025). "Patients with this type of diabetes require insulin injections because their bodies cannot produce enough insulin." (PMID 40062236, 2025). "In the pancreas, HNF-1β regulates genes essential for beta-cell function and insulin production, directly linking its haploinsufficiency to the onset of diabetes." (PMID 41009948, 2025). "IGFs have also been increasingly recognized as a potential therapeutic target in a variety of conditions, including osteoporosis, diabetes, obesity, neuromuscular disorders, and resistance to growth hormone and insulin." (PMID 40733109, 2025). "All stakeholders in insulin therapy should be involved, particularly the diabetes education specialists." (PMID 40376558, 2025).
diabetes (continued). "cGMP-dependent protein kinase, which was identified in our findings, plays a significant role in vascular function and insulin signaling, highlighting its relevance in the context of diabetes and metabolic syndrome." (PMID 39941463, 2025). "Patients with diabetes were excluded, as insulin insensitivity is essential for identifying metabolic abnormalities and differentiating them from the metabolically healthy groups." (PMID 41373582, 2025). "The efficacy of sulfonylureas in patients with KCNJ11-related diabetes has been well established, with studies demonstrating successful transition from insulin to oral therapy in the majority of cases." (PMID 41367630, 2025). "Diabetes mellitus is a common metabolic disorder characterized by hyperglycemia, resulting from impaired insulin secretion or action; its prevalence continues to rise." (PMID 40864768, 2025). "Collectively, these effects regulate insulin secretion and modulate insulin resistance, positioning MSCs as a therapeutic approach for diabetes management." (PMID 39851765, 2025). "The medicines that are available for the management of diabetes mellitus are broadly classified into two categories: insulin or oral hypoglycemic drugs." (PMID 39791180, 2025). "A key feature of β-cell dysfunction in diabetes is the impairment of biphasic insulin secretion, which consists of an initial rapid release followed by a sustained phase." (PMID 40154614, 2025). "Despite the acceptable level of knowledge and practices regarding insulin self-administration, the study highlights critical gaps that require attention in both local and global diabetes care frameworks." (PMID 40471961, 2025). "Our data also highlights the potential for L. edulis in contributing to endogenous insulin production, which is pivotal for glycemic control in diabetes management." (PMID 40822470, 2025). "The conventional view of the history of diabetes suggests a reduced insulin sensitivity followed by increased insulin secretion to maintain glucose homeostasis." (PMID 39471069, 2025). "Insulin therapy is used to treat insulin insufficiency or resistance among patients with diabetes mellitus." (PMID 40564223, 2025). "Older adults are also a heterogenous group with a diverse range of physical and mental capabilities, with differing needs in terms of their ability to self‐manage insulin, and who therefore require tailored, individualised diabetes care." (PMID 41358572, 2025). "Several studies analyzing the link between DISH and diabetes have suggested that a possible pathogenesis is that high levels of insulin or insulin-like growth factor stimulate new bone formation." (PMID 40444238, 2025). "In this Position Statement, we focus on minimum standards of diabetes care, insulin regimens and recommended glycaemic targets for residents with T1D." (PMID 39500566, 2025). "Accordingly, zinc supplementation has been shown to enhance glucose control and insulin sensitivity in patients with diabetes mellitus." (PMID 40869403, 2025). "Diabetes management in end‐stage kidney disease (ESKD) is complicated by altered insulin pharmacokinetics and glucose metabolism, particularly in the context of hemodialysis (HD)." (PMID 41174864, 2025). "We conducted a 24-week single-arm prospective study to evaluate the impact of iDegLira compared to premixed insulin on the regulation of diabetes and glucovariability using continuous glucose monitoring (CGM), HbA1c, and anthropometric measurements." (PMID 41268167, 2025). "A comparison between GLP-1 agonists and placebo on the total daily insulin dose, and HbA1c among patients with type 1 diabetes mellitus." (PMID 40852189, 2025). "Over time, this can place increased demand on the pancreas to produce more insulin, potentially leading to β-cell exhaustion and the onset of diabetes." (PMID 40076938, 2025).